PYGM (glycogen phosphorylase, muscle associated)
Description:
Allosteric enzyme that catalyzes the rate-limiting step in glycogen catabolism, the phosphorolytic cleavage of glycogen to produce glucose-1-phosphate, and plays a central role in maintaining cellular and organismal glucose homeostasis.
Synonyms: GSD5
Tractability: Small molecule: a structure with a bound ligand is known; it has a binding pocket of medium quality; it belongs to a druggable protein family. PROTAC: ubiquitination databases record sites on it; a small molecule that binds it is known.
Target class: Enzyme; Transferase
Gene: Protein-coding gene on chromosome 11 (64,746,389 to 64,759,974, reverse strand). Ensembl gene ENSG00000068976.
Pathways (Reactome):
Metabolism: Glycogen breakdown (glycogenolysis)
Gene Ontology:
Molecular function: 1,4-alpha-oligoglucan phosphorylase activity; glycogen phosphorylase activity; protein binding; pyridoxal phosphate binding
Biological process: glycogen catabolic process; glycogen metabolic process; carbohydrate metabolic process
Cellular component: extracellular exosome; cytosol
Genetic constraint (gnomAD): Loss-of-function variants: 81 observed, 101.26 expected, observed/expected ratio (o/e) 0.8, 90% interval 0.67 to 0.96. The upper end of that interval is the gene's LOEUF score, 0.96, which puts it in group 4 of 6, group 1 being the genes least tolerant of losing a copy. Missense variants: 1,030 observed, 1,189.8 expected, observed/expected ratio (o/e) 0.87, 90% interval 0.82 to 0.91. Synonymous variants: 436 observed, 456.14 expected, observed/expected ratio (o/e) 0.96, 90% interval 0.88 to 1.03.
Gene-disease validity (ClinGen):
ClinGen rates the evidence that PYGM causes each of these diseases.
glycogen storage disease V (autosomal recessive): Definitive. Myophosphorylase deficiency (McArdle's disease), or glycogen storage disease type 5 (GSD5), is a severe form of glycogen storage disease characterized by exercise intolerance.
Homologues: Orthologues: chimpanzee PYGM (99% identical), macaque PYGM (99% identical), dog PYGM (98% identical), guinea pig PYGM (97% identical), mouse Pygm (97% identical), rat Pygm (97% identical), rabbit PYGM (96% identical), pig PYGM (93% identical), tropical clawed frog pygb (86% identical), zebrafish pygma (85% identical), zebrafish pygmb (83% identical), Drosophila melanogaster Glyp (73% identical), and 1 more. Paralogues in human: PYGB (84% identical), PYGL (80% identical).
Diseases named in the same sentence as PYGM in open-access papers:
PYGM is named in the same sentence as 57 diseases in open-access papers, as found by Europe PMC text mining. Sharing a sentence is not in itself a finding about the gene and the disease. The quoted sentences say what the papers report.
McArdle disease (41 papers, 2010 to 2026). "Molecular analysis was performed, identifying the homozygous pathogenic variant c.280C>T (p.Arg94Trp) in the PYGM gene and confirming the diagnosis of McArdle disease." (PMID 41835783, 2026). "McArdle disease (GSD-V) is a myopathy secondary to a deficiency in myophosphorylase enzyme due to a mutation in the PYGM gene." (PMID 39803349, 2025). "McArdle disease, or glycogen storage disease type V, is a rare autosomal recessive disorder caused by mutations in the PYGM gene, which encodes the muscle-specific isoform of glycogen phosphorylase." (PMID 40051944, 2025). "Given his clinical history and episodic muscle weakness, whole-exome sequencing was performed, which confirmed pathogenic variants in the PYGM gene, establishing the diagnosis of McArdle disease." (PMID 40051944, 2025). "WES was performed, which identified pathogenic variants in the PYGM gene (1176C>T and 855+1G>A), confirming the diagnosis of glycogen storage disease type V (McArdle disease)." (PMID 40051944, 2025). "A female diagnosed with ROMS at 20–29 years of age was shown to be homozygous for a pathogenic variant in PYGM, an established cause of McArdle disease." (PMID 41372986, 2025). "McArdle disease or glycogen storage disease Type V is a genetic condition caused by PYGM gene mutations leading to exercise intolerance and fatigability." (PMID 39803349, 2025). "To date, around 150 mutations in the human PYGM gene have been identified, with the p.R50X nonsense mutation in exon 1 being the most prevalent in Caucasians with McArdle disease." (PMID 40051944, 2025). "Glycogen storage disease type 5 (GSD) is an autosomal recessive metabolic myopathy caused by pathogenic variants in the PYGM gene." (PMID 39981214, 2025). "Among the genes related to glycogen catabolism, PYGB, PYGL, and PYGM, only PYGM is expressed in muscle, which will lead to McArdle disease when it carries biallelic mutations." (PMID 38334681, 2024). "In humans, there are 147 pathogenic variants and 39 polymorphisms related to an autosomal-recessive disorder in PYGM termed McArdle’s disease." (PMID 38678201, 2024). "McArdle disease, also known as glycogen storage disease type V, is an autosomal recessive disorder that is caused by the glycogenolysis disorder of the skeletal muscle due to PYGM defect." (PMID 38334681, 2024). "PYGM loss causes McArdle disease or glycogen storage disease (type V) and has been associated with vision loss due to atrophy of the outer retina and RPE, manifesting as a pattern retinal dystrophy." (PMID 39009342, 2024). "Genetic analysis confirmed the diagnosis of McArdle disease showing the common homozygous p.Arg50 stop codon mutation in PYGM gene." (PMID 38802689, 2024). "Loss of glycogen myophosphorylase (PYGM) expression results in an inability to break down muscle glycogen, leading to McArdle disease—an autosomal recessive metabolic disorder characterized by exercise intolerance and muscle cramps." (PMID 39009342, 2024). "All pathogenic PYGM mutations identified in the present study have been previously reported in the last update of the Spanish registry of patients with McArdle disease." (PMID 36370371, 2023). "McArdle disease is a rare inherited condition caused by mutations in the PYGM gene, which codes for the muscular isoform of glycogen phosphorylase or myophosphorylase." (PMID 37760875, 2023). "McArdle disease or GSD V (OMIM #608455) is a glycogen storage disorder caused by mutations in the PYGM gene encoding an enzyme called myophosphorylase." (PMID 37239314, 2023). "In summary, we report here the first human iPSC-based skeletal muscle model of McArdle disease carrying the second most frequent pathogenic variant in the PYGM gene in the Spanish population: NM_005609.4: c.2392T>C (p.Trp798Arg)." (PMID 37760875, 2023).
McArdle disease (continued). "In genes related to glycogen catabolism, PYGB, PYGL, and PYGM, only PYGM is expressed in the muscle, and when carrying biallelic mutations it causes McArdle disease (glycogen storage disease type V)." (PMID 37185710, 2023). "In this article, we present a human iPSC-based skeletal muscle model of McArdle disease carrying the second most frequent mutation in PYGM in the Spanish population: NM_005609.4: c.2392T>C (p.Trp798Arg)." (PMID 37760875, 2023). "In summary, to the best of our knowledge, this is the first human model of McArdle disease carrying the missense mutation in the PYGM gene: NM_005609.4: c.2392T>C (p.Trp798Arg)." (PMID 37760875, 2023). "Here, we present the generation of a human iPSC-based skeletal muscle model of McArdle disease carrying the second most frequent pathogenic variant in the Spanish population in the PYGM gene, NM_005609.4: c.2392T>C (p.Trp798Arg)." (PMID 37760875, 2023). "As far as we know, this is the only human cellular model of McArdle disease for a missense variant in PYGM generated with iPSC technology." (PMID 37760875, 2023). "There are four animal models available for the study of McArdle disease: two spontaneous models in Charolais cattle and Merino sheep, a knock-in the mouse model for the PYGM p.R50* mutation and a zebrafish model." (PMID 36430443, 2022). "P100 was a 5-year-old girl with homozygous variants in TRAPPC11, associated with limb-girdle muscular dystrophy, and PYGM, associated with McArdle disease." (PMID 35628876, 2022). "Glycogen storage disease type V (GSDV, McArdle disease) is a rare genetic myopathy caused by deficiency of the muscle isoform of glycogen phosphorylase (PYGM)." (PMID 35563042, 2022). "To date, more than 150 mutations have been described in the PYGM gene associated with McArdle disease, the nonsense mutation c.148C>T; p.R50* being the most prevalent in the Caucasian population." (PMID 36430443, 2022). "More than 170 pathogenic mutations (including missense, nonsense, in-frame, frameshift, and splicing variants) have been identified in the PYGM gene that cause McArdle disease." (PMID 35563042, 2022). "McArdle disease is an autosomal recessive disorder of muscle glycogen metabolism caused by pathogenic mutations in the PYGM gene, which encodes the skeletal muscle-specific isoform of glycogen phosphorylase." (PMID 35052414, 2021). "PYGM is implicated in several pathological states, such as muscle glycogen phosphorylase deficiency (McArdle disease), schizophrenia, and cancer." (PMID 33924466, 2021). "This phenomenon probably contributes to effective creation of animal research models of the disease caused by PYGM deficiency, McArdle disease." (PMID 33924466, 2021). "Since McArdle disease is thought to be an autosomal recessive disorder, all patients should have a pathogenic variant in both copies of the PYGM gene (homozygous or compound heterozygous)." (PMID 32735634, 2020). "In one of them, three-point mutations were identified in the PYGM gene among 40 patients with McArdle disease." (PMID 31775340, 2019). "McArdle disease is an autosomal recessive disease due to complete deficiency of myophosphorylase (PYGM) activity." (PMID 31861911, 2019). "Traditionally, McArdle disease has been considered a metabolic myopathy caused by the lack of expression of the muscle isoform of the glycogen phosphorylase (PYGM)." (PMID 31775340, 2019). "McArdle disease (glycogen storage disease type V) is a rare metabolic myopathy (estimated prevalence, 1/100 000) resulting from biallelic mutations in the PYGM gene, encoding muscle glycogen phosphorylase (reviewed by Lucia et al1)." (PMID 30316539, 2019). "Deficiency in muscle glycogen phosphorylase PYGM causes a glycogen storage disease type V (also known as GSDV or McArdle disease)." (PMID 26882899, 2016).
McArdle disease (continued). "Since the publication of the first pathogenic PYGM mutations in 1993, a growing allelic heterogeneity of the PYGM gene has been reported, with more than 100 mutations known to cause McArdle's disease." (PMID 20957198, 2010). "Mutations in the PYGM gene encoding skeletal muscle glycogen phosphorylase (GP) cause a metabolic disorder known as McArdle's disease." (PMID 20957198, 2010). "Further research may be directed in the future in determining whether variants of the PYGM gene mutation affect the age of onset of McArdle's disease." (PMID 39803349, 2025). "Furthermore, we uncovered the effects of a novel pathogenic splicing variant in PYGM on isoforms in a compound-heterozygous case of McArdle disease using nanopore cDNA amplicon and targeted genomic sequencing." (PMID 40781467, 2025). "Clinical and genetic analyses of the cattle confirmed the presence of Glycogen Storage Disease Type V (GSD-V) associated with a nonsense variant in PYGM in these composite calves attributed to a variant distinct from that previously identified in Charolais cattle." (PMID 38678201, 2024). "McArdle disease is a rare autosomal recessive condition caused by mutations in the PYGM gene." (PMID 37760875, 2023). "McArdle disease is a rare autosomal recessive disorder caused by mutations in the PYGM gene." (PMID 36430443, 2022). "So far, 206 mutations in the PYGM gene leading to McArdle disease development have been described." (PMID 33924466, 2021). "Interestingly, the expression of TNNC1 and TNNC2 genes was also shown to be significantly down-regulated in the case of PYGM deficiency (McArdle) disease." (PMID 33924466, 2021). "McArdle disease is caused by pathogenic mutations in both copies of the gene (PYGM) encoding the muscle isoform of glycogen phosphorylase (GP-M), generally leading to loss of activity and inability to break down glycogen, making this source of energy unavailable to patients." (PMID 31848135, 2020). "The disease was later associated with myophosphorylase deficiency caused by mutation PYGM gene." (PMID 33153458, 2020). "In order to test our hypothesis, we evaluated the association of PYGM mRNA expression in patients with phenotypic variations of McArdle disease." (PMID 32735634, 2020). "In McArdle disease patients, the PYGM gene (11q13) mutations inactivate the enzyme." (PMID 31775340, 2019). "Homozygous or compound heterozygous mutations in PYGM (OMIM #608455) cause glycogen storage disease type V (GSDV, McArdle disease) which is characterized by the absence of skeletal muscle glycogen phosphorylase, resulting in an inability to convert muscle glycogen into glucose-1-phosphate." (PMID 25929793, 2015). "Mutations in the muscle isoform of mammalian glycogen phosphorylase (PYGM) cause glycogen storage disease type V (also known as McArdle's Disease), while mutations in the liver isoform (PYGL) cause glycogen storage disease type VI (also known as Hers' disease)." (PMID 24265594, 2013). "Following a muscle biopsy, skeletal muscle enzymatic assay, and genetic testing, he was diagnosed with late-onset McArdle's disease (homozygous PYGM genotype)." (PMID 39803349, 2025). "McArdle disease, or glycogen storage disease type V (OMIM 232600), is a rare autosomal recessive disorder caused by mutations in the PYGM gene." (PMID 37760875, 2023). "McArdle disease (also known as glycogen storage disease type V, OMIM 232600) is an autosomal recessive rare disorder caused by mutations in the PYGM gene." (PMID 36430443, 2022). "This study compared different aspects of McArdle’s disease: clinical, demographic, laboratorial and genetic data in relation to PYGM mRNA expression." (PMID 32735634, 2020). "If the patients have clear suspicion of McArdle disease, sequencing of the whole PYGM gene is recommended." (PMID 32075227, 2020). "Further, we summarize the expression and functional significance of PYGM in other tissues than skeletal muscle both in health and McArdle disease." (PMID 31775340, 2019).
McArdle disease (continued). "One patient that developed muscular complaints only after CVT was homozygous for PYGM 49XX, a genotype of McArdle disease." (PMID 31861911, 2019). "The most commonly identified predisposing conditions of ER are deficiencies of carnitine palmitoyltransferase II (CPT2 gene, OMIM *600650), myophosphorylase (McArdle disease, PYGM gene, OMIM *608455), and myoadenylate deaminase (AMPD1 gene, OMIM +102770)." (PMID 23476141, 2013). "And among 15 splicing variants identified in Patient2 with McArdle disease, no variants were found in PYGM, which is the causative gene for McArdle disease." (PMID 40781467, 2025). "The diagnosis of McArdle disease can be confirmed via genetic testing, identifying pathogenic mutations in the PYGM gene, or through muscle biopsy, which demonstrates absent myophosphorylase activity." (PMID 39834954, 2024). "The isogenic iPSC model for McArdle disease (composed by the line MA1-B9 as isogenic control and the line MA1 as McArdle line harbouring the mutation c.148C>T; p.R50* in the PYGM gene) was employed to evaluate the action of two read-through compounds as possible therapy." (PMID 36430443, 2022). "McArdle disease is a myopathy caused by mutations in PYGM gene that is characterized by reduced or absent activity of myophosphorylase." (PMID 33153458, 2020). "Further, genetic screenings have demonstrated that these patients present mutations in the PYGM gene and not in the known dystrophy-causing genes, thus showing a possible relationship between retinopathy and McArdle disease." (PMID 31775340, 2019). "Although PYGM expression still needs to be measured in these cells, four McArdle disease case reports with RPE dystrophy may indicate that this dystrophy can be related to PYGM mutations." (PMID 31775340, 2019). "This includes PYGM-deficiency (McArdle disease); lack of AMPD1, which causes metabolic myopathy in humans; and loss-of-function mutations in the CAPN3 gene that have been associated with limb-girdle muscular dystrophy type 2A (LGMD2A)." (PMID 20175888, 2010). "To conclude, we have reported a novel PYGM mutation, p.R771PfsX33, in two brothers with McArdle's disease, which causes reduction in PYGM mRNA, absence of protein and GP activity." (PMID 20957198, 2010). "It is presumed that PYGM may contribute not only to McArdle disease but also to other conditions." (PMID 40051944, 2025). "We investigated genetic variation in PYGM considering the number of PTCs (premature termination codon) per sample and compared mRNA expression in skeletal muscle samples from 15 patients with McArdle disease and 16 controls to PTCs number and different aspects of the disease." (PMID 32735634, 2020). "It was also observed that the glucose metabolism pathways, which were activated to compensate for the lack of PYGM, are different in the mouse model and humans affected by McArdle disease." (PMID 33924466, 2021). "Given that the PYGM gene is solely responsible for the formation of the muscle isoform of glycogen phosphorylase and that the hepatic and cardiac isoforms are not affected, McArdle's disease is understood to be a pure myopathy." (PMID 39318660, 2024). "However, it could be postulated that in McArdle disease, the lack of PYGM activity could affect not only ATP generation, but also PTM processes, altering the O-GlcNAcylation of some proteins and affecting other tissues than skeletal muscle, such as the immune system and/or the brain." (PMID 31775340, 2019).
glycogen storage disease (8 papers, 2015 to 2025). "For example, biallelic loss of function in PYGM causes glycogen storage disease which can lead to muscle atrophy and an increase in adipose tissue." (PMID 35896531, 2022). "For example, in GSD type V (McArdle disease; MIM #232600), a glycogen storage disease, heterozygous individuals carrying just one copy of the PYGM gene may develop muscle symptoms that are probably related to the critically low residual level (30–40%) of myophosphorylase activity in muscle." (PMID 37628614, 2023). "Lack of PYGM in the liver can cause Hers disease, a glycogen-storage disease." (PMID 35990602, 2022).
metabolic myopathy (6 papers, 2010 to 2025). A group of rare inherited disorders characterized by a deficiency of enzymes that are involved in metabolic pathways that affect muscles. "Glycogen storage disease type 5 (GSD 5, Mc Ardle's disease) is an autosomal recessive metabolic myopathy caused by pathogenic variants in the PYGM gene leading to myophosphorylase deficiency." (PMID 39981214, 2025). "Rare variants in several metabolic myopathy genes including CACNA1S, CPT2, LPIN1, PYGM and RYR1 increase myopathy/rhabdomyolysis risk following statin exposure." (PMID 31861911, 2019).
rhabdomyolysis (6 papers, 2015 to 2025). Necrosis or disintegration of skeletal muscle often followed by myoglobinuria. "It is an autosomic recessive disorder that is caused by mutations in the PYGM gene and typically presents with exercise intolerance, i.e. episodes of early exertional fatigue frequently accompanied by rhabdomyolysis and myoglobinuria." (PMID 25762569, 2015).
breast carcinoma (3 papers, 2019 to 2022). "PYGM, a gene involved in glycogen metabolism, has been illuminated to be down-regulated in breast cancer and its expression was related with patients survival time." (PMID 31324732, 2019). "Additionally, as an important enzyme in the first step of glycogenolysis, PYGM was found to be less expressed in tumor tissues than that in normal tissues, which made an impact on the survival of breast cancer patients." (PMID 34194464, 2021).